TSPO (translocator protein)
Description:
Can bind protoporphyrin IX and may play a role in the transport of porphyrins and heme (By similarity). Promotes the transport of cholesterol across mitochondrial membranes and may play a role in lipid metabolism, but its precise physiological role is controversial. It is apparently not required for steroid hormone biosynthesis. Was initially identified as peripheral-type benzodiazepine receptor; can also bind isoquinoline carboxamides.
Synonyms: PBR; BZRP; MBR; PKBS; mDRC; DBI; IBP; pk18; TSPO1; BPBS; PBS; PTBR
Tractability: Small molecule: an approved drug acts on it; a high-quality ligand is known; it belongs to a druggable protein family. Antibody: UniProt predicts a signal peptide or a membrane-spanning region. PROTAC: its protein half-life has been measured; a small molecule that binds it is known.
Target class: Membrane receptor
Safety:
Unwanted effects reported when the protein is acted on. In parentheses: how it was acted on, where the effect was seen, and who reports it.
convulsions (activation, acute dosing; immune, central nervous system; source: Lynch et al. (2017))
decreased anxiety (activation, acute dosing; immune, central nervous system; source: Lynch et al. (2017))
decreased convulsions (inhibition, acute dosing; immune, central nervous system; source: Lynch et al. (2017))
decreased inflammation (inhibition, acute dosing and activation, acute dosing; immune, central nervous system; source: Lynch et al. (2017))
impaired, Fertility (inhibition; source: AOP-Wiki)
Malformation, Male reproductive tract (inhibition; source: AOP-Wiki)
Gene: Protein-coding gene on chromosome 22 (43,151,077 to 43,163,246, forward strand). Ensembl gene ENSG00000100300.
Subcellular location: Mitochondrion membrane
Subcellular location (Human Protein Atlas): Mitochondria; Cytosol; Vesicles
Pathways (Reactome):
Metabolism: Pregnenolone biosynthesis
Gene Ontology:
Molecular function: protein binding; benzodiazepine receptor activity; cholesterol binding; cholesterol transfer activity; androgen binding; transmembrane transporter binding
Biological process: C21-steroid hormone biosynthetic process; heme biosynthetic process; monoatomic anion transport; regulation of cell population proliferation; regulation of cholesterol transport; steroid metabolic process; adrenal gland development; behavioral response to pain; cellular hypotonic response; cellular response to lipopolysaccharide; cellular response to zinc ion; chloride transport; cholesterol homeostasis; contact inhibition; glial cell migration; maintenance of protein location in mitochondrion; monoatomic ion transport; negative regulation of ATP metabolic process; negative regulation of corticosterone secretion; negative regulation of glial cell proliferation; negative regulation of mitophagy; negative regulation of nitric oxide biosynthetic process; negative regulation of protein ubiquitination; negative regulation of tumor necrosis factor production; peripheral nervous system axon regeneration; and 18 more
Cellular component: extracellular exosome; mitochondrion; mitochondrial outer membrane; membrane; mitochondrial membrane
Genetic constraint (gnomAD): Loss-of-function variants: 16 observed, 11.85 expected, observed/expected ratio (o/e) 1.35, 90% interval 0.9 to 1.87. The upper end of that interval is the gene's LOEUF score, 1.87, which puts it in group 6 of 6, group 1 being the genes least tolerant of losing a copy. Missense variants: 232 observed, 195.89 expected, observed/expected ratio (o/e) 1.18, 90% interval 1.06 to 1.32. Synonymous variants: 114 observed, 89.32 expected, observed/expected ratio (o/e) 1.28, 90% interval 1.1 to 1.49.
Homologues: Orthologues: macaque TSPO (98% identical), chimpanzee TSPO (98% identical), pig TSPO (83% identical), dog TSPO (82% identical), mouse Tspo (81% identical), guinea pig TSPO (80% identical), rat Tspo (80% identical), tropical clawed frog tspo (59% identical), Drosophila melanogaster Tspo (41% identical), Caenorhabditis elegans tspo-1 (30% identical). Paralogues in human: TSPO2 (37% identical).
Diseases named in the same sentence as TSPO in open-access papers:
TSPO is named in the same sentence as 289 diseases in open-access papers, as found by Europe PMC text mining. Sharing a sentence is not in itself a finding about the gene and the disease. The quoted sentences say what the papers report.
Alzheimer disease (101 papers, 2012 to 2025). A progressive, neurodegenerative disease characterized by loss of function and death of nerve cells in several areas of the brain leading to loss of cognitive function such as memory and language. "Within this multi-modal PET/MRI imaging study we have shown that carriers of the rare TREM2 p.R47H Alzheimer’s disease risk variant have lower levels of TSPO tracer uptake in brain regions known to be affected in early Alzheimer’s disease." (PMID 37990275, 2023). "TSPO has also been associated with the development of Alzheimer’s disease and Parkinson’s disease due to dysfunctional mitochondria." (PMID 38288111, 2023). "Researchers have previously employed TSPO PET imaging time series to characterize neuroinflammation associated with animal disease models of conditions including Alzheimer’s disease, stroke, seizure, and multiple sclerosis." (PMID 35113011, 2022). "TSPO has recently been identified as a potential biomarker of neurodegeneration since its expression increases with inflammation and neurodegeneration associated with Alzheimer’s disease, HIV encephalitis, and MS." (PMID 40732235, 2025). "Due to this, TSPO is extensively studied as a biomarker of neuroinflammation caused by different pathologies, such as FM, chronic pain, neuropathies and neurological diseases including Alzheimer’s disease (AD), PD and MS." (PMID 41465288, 2025). "Since inflammation is tightly linked to neuronal dysfunction and loss in Alzheimer’s disease (AD), TSPO could represent a promising tool for neuroinflammation detection and in particular, in conditions such as AD." (PMID 37189346, 2023). "However, this is not the case, as schizophrenia seems to be associated with a decrease in TSPO, while Alzheimer’s disease shows an increase in TSPO." (PMID 32839410, 2020). "TSPO has been implicated in neurodegenerative and neuroinflammatory processes, as presumed by the observation of increased TSPO expression in various neuropathologies such as Alzheimer’s disease, multiple sclerosis, Parkinson’s disease, and major depressive disorder (MDD)." (PMID 39684592, 2024). "TSPO also has been implicated in the diabetes-inducing neurophysiological and structural changes in the central nervous system (CNS), and is associated with cognitive deficits and increased risk of dementia, stroke, cerebrovascular events, Alzheimer’s disease, and psychiatric disorders." (PMID 32093016, 2020). "An increase in pTSPO reflecting an increase in TSPO density for frontal, parietal, temporal, and occipital lobes was reported for Alzheimer’s disease patients in line with previous general references." (PMID 39975931, 2025). "TSPO expression in activated microglia is upregulated in Alzheimer's disease (AD), representing both a biomarker and therapeutic target for neuroinflammation." (PMID 40225565, 2025). "In Alzheimer’s disease (AD) animal models, TSPO’s upregulation is detected first in astrocytes, then in microglia." (PMID 41152868, 2025). "Here we investigated the interaction between aging and TSPO immunomodulatory function in the mouse hippocampus, a region severely affected in Alzheimer's Disease (AD)." (PMID 40275629, 2025). "Prior studies investigating the role of TSPO in the pathophysiology of Alzheimer’s disease have yielded conflicting outcomes." (PMID 37891168, 2023). "Translocator protein has been closely tied to neurodegenerative diseases like Alzheimer’s Disease (AD) and Parkinson’s Disease (PD), due to the presence of dysfunctional mitochondria, and the increased inflammation as the innate response to degradation." (PMID 37416505, 2023). "In Alzheimer's disease, there have been many studies investigating microglial activation with TSPO PET and clinical severity (see52 for a recent review)." (PMID 36883644, 2023).
Alzheimer disease (continued). "The relationship between neuroinflammation and the clinical features of Alzheimer’s disease (AD) have been the subject of several positron emission tomography (PET) studies of the translocator protein (TSPO)." (PMID 37588670, 2023). "A significant increase of TSPO in astrocytes has been found in neurodegenerative diseases, such as Alzheimer’s disease and amyotrophic lateral sclerosis." (PMID 36614916, 2022). "These approaches have been used in clinical studies that used TSPO images to explore a variety of disorders, including Alzheimer’s disease, Parkinson’s disease, amyotrophic lateral sclerosis, psychosis, and glioma." (PMID 33693967, 2021). "This analysis was extended to two Alzheimer’s disease’s markers,amyloid and inflammation, by quantifying amyloid plaques and TSPO." (PMID 34286270, 2021). "TSPO imaging has been used to track disease severity and the efficacy of treatments in neurodegenerative disorders, such as Alzheimer’s disease and dementia." (PMID 33800685, 2021). "The SVCA method for 11C-(R)-PK11195 has been extensively used to study several neurological and psychiatric conditions, including Alzheimer’s disease, multiple sclerosis, traumatic brain injury, schizophrenia and changes in TSPO expression in normal ageing." (PMID 33779770, 2021). "One such TSPO radiotracer 11C-PK11195 has demonstrated increased ligand binding in neurodegenerative diseases including Alzheimer’s disease, but there is little data for TSPO PET in SVD." (PMID 34000009, 2021). "In contrast, other clinical studies reported an increase in TSPO in the hippocampus in Alzheimer’s disease, as well as in mild cognitive impairment (MCI) patients." (PMID 32839410, 2020). "In contrast to these data, most clinical studies reported an increase in TSPO in Alzheimer’s disease." (PMID 32839410, 2020). "Our results suggest that [18F]DPA714, a molecular probe targeting TSPO, has great potential in monitoring microglia activation and neuroinflammation and discovering the best time point of anti-inflammatory therapy for Alzheimer's disease." (PMID 33132817, 2020). "In humans, although efforts still need to be made to better characterize the presence of TSPO, it is now widely accepted that it is overexpressed in brain regions in Alzheimer’s disease patients." (PMID 32839410, 2020). "In fact, while age probably influences the density of TSPO and gender influences neuropathological and clinical progressions of Alzheimer’s disease, in some studies, participants in the patients’ and the control group were not age- or sex-matched." (PMID 32839410, 2020). "In the Schuitemaker study, the authors also found that TSPO levels were comparable between prodromal Alzheimer’s disease patients who progressed to dementia and those who remained stable during the follow-up period (2.7 years, range: 2.3–3.3)." (PMID 32839410, 2020). "This study aimed to test the ability of TSPO to detect activated WM microglia that are immunohistochemically positive for MHCII in rat models of prodromal Alzheimer’s disease and acute subcortical stroke." (PMID 32990808, 2020). "For example—and with regard to time-course—prior TSPO studies primarily examined disorders marked by chronic neuroinflammation, such as Alzheimer’s disease." (PMID 32359360, 2020). "Alzheimer’s disease is the most studied pathology in terms of changes in TSPO, in humans and in animal models." (PMID 32839410, 2020). "Alzheimer’s disease is one of the pathologies with the largest number of studies reporting the use of in vivo imaging of TSPO." (PMID 32839410, 2020). "In the last part, Alzheimer’s disease will be used as an example to address the physiological and pathological role of TSPO." (PMID 32839410, 2020). "Previous studies have found that the expression of TSPO is significantly increased when the nervous system is damaged, especially in Alzheimer’s disease, Parkinson’s disease, Huntington’s disease and Amyotrophic Lateral Sclerosis." (PMID 33708121, 2020).
Alzheimer disease (continued). "18F-GE-180 provided higher sensitivity to detect microglial activation and its changes under therapy in a mouse model of Alzheimer’s disease compared to the second-generation TSPO tracer 18F-PBR06." (PMID 32322915, 2020). "A final limitation of clinical studies of TSPO in Alzheimer’s disease is the number of participants: Ranging from 6 to 20 across studies." (PMID 32839410, 2020). "In this section, the links between TSPO, the molecular actors of Alzheimer’s disease (amyloid and Tau) and clinical symptoms will be described." (PMID 32839410, 2020). "The number of studies concerning TSPO in other psychiatric and neurodegenerative pathologies is much less important than in the case of Alzheimer’s disease." (PMID 32839410, 2020). "Among other pathologies, studies on schizophrenia which demonstrate different alterations in TSPO levels from those observed in Alzheimer’s disease will also be described in detail." (PMID 32839410, 2020). "The interpretation of the TSPO signal in the entorhinal cortex (one of the regions involved early in the course of Alzheimer’s disease) also seems to depend on this method of quantification." (PMID 32839410, 2020). "It has been widely reported that overexpression of TSPO can result in microglial activation and is thereby involved in neurodegenerative disorders, such as Parkinson disease (PD), Alzheimer disease (AD), and Huntington disease (HD)." (PMID 32252470, 2020). "The ligands of TSPO have been evaluated as protective agents to evaluate the inflammatory status in the brains of patients with Alzheimer’s Disease (PK11195 and Ro5-4864), anxiety (XBD-173), MS (PK11195) and acute lung injury (ALI)." (PMID 27907096, 2016). "Augmented TSPO expression has been demonstrated in different diseases such as Alzheimer's disease, multiple sclerosis, encephalitis, and stroke." (PMID 24982880, 2014). "In the 3xTgAD mouse model of Alzheimer's disease, TSPO activation was shown to enhance steroidogenesis and neuroprotection." (PMID 24877623, 2014). "TSPO has been proposed as a biomarker of neuroinflammation and a new drug target in neurological diseases ranging from Alzheimer’s disease to anxiety." (PMID 25406832, 2014). "Recently, it has been hypothesized that peripheral monocytes’ recruitment through the blood-brain barrier may contribute to the increase of TSPO levels in the central nervous system observed in the context of inflammation and Alzheimer’s disease." (PMID 39475881, 2024). "Accordingly, using PET imaging, increased TSPO signal has been observed in a range of human neurodegenerative diseases with an inflammatory component, such as simian immunodeficiency virus encephalitis, multiple sclerosis, Huntington’s and Alzheimer’s disease." (PMID 37032328, 2023). "Similarly, others have found that TSPO positive microglia, astrocytes and endothelium are all increased in models of Alzheimer’s-like neurodegeneration and in postmortem human Alzheimer’s disease brains." (PMID 37032328, 2023). "Increased TSPO expression in the hippocampus, amygdala, and thalamus has been implicated with reduced cognitive performance in patients with HIV, and with disease progression in Alzheimer's disease." (PMID 37885823, 2023). "In contrast, no astrocytic cell proliferation accompaniedthe TSPOoverexpression in the cortex of subjects with Alzheimer’s disease, which could suggest different roles of TSPO depending on the brainregion as well as the cell type." (PMID 37663488, 2023). "The primary aim of this study was to investigate if TREM2 p.R47H risk variant carriers have reduced in vivo microglial activation, measured using TSPO signal, compared to non-carriers also at increased risk of Alzheimer’s disease." (PMID 37990275, 2023). "Moreover, one of the main neuroinflammation biomarker used in clinical research is the 18-kDa translocator protein (TSPO), as it is overexpressed in many brain diseases, including Alzheimer’s disease." (PMID 36550510, 2022).